INS (insulin)
Diseases named in the same sentence as INS in open-access papers (continued):
Sharing a sentence is not in itself a finding about the gene and the disease.
Obesity (continued). "A diet‐induced obesity model, previously characterized by our group, presented increased body and trunk fat percentages, higher triglyceride, total cholesterol, and insulin and leptin levels compared with lean animals, as well as greater adipose tissue compartments normalized by body weight." (PMID 34632734, 2021). "Some obesity/T2DM-associated factors and mechanisms, related to inflammatory pathways, could modulate peripheral insulin signaling." (PMID 34070553, 2021). "During obesity, M1-like macrophage numbers elevate due to augmented levels of free fatty acids (FFAs), cholesterol, LPS, and hypoxia, contributing to adipose tissue (AT) inflammation and inhibition of insulin signaling." (PMID 34357044, 2021). "In summary, although the efficacy of Ginsenoside in improving insulin sensitivity is questionable, ginsenosides show strong potential for regulating glucose and lipid metabolism, and thus conferring metabolic benefits on obesity." (PMID 34512356, 2021). "Metabolic syndrome and its components have been widely considered to be correlated with the initiation and progression of breast cancer, which is due to obesity and its related adipokines, insulin and IGFs, abnormal serum lipids and lipoproteins and the molecules leading to hypertension." (PMID 33842335, 2021). "M2-related anti-inflammatory cytokine such as IL-10 in EAT might act as a compensatory mechanism involving the insulin-signaling pathway to maintain glucose homeostasis in obesity." (PMID 34266493, 2021). "However, phosphatase and tensin homolog (PTEN) and protein-tyrosine phosphatase-1B (PTP-1B), both inhibitory regulators for insulin action, were increased in obesity but decreased after exercise." (PMID 34234788, 2021). "Moreover, AET intervention improves insulin sensitivity in adolescents with obesity and low HOMA-IR." (PMID 34488728, 2021). "Notably, a pathway analysis demonstrated a connection between ASTN2 and plasma triglycerides which further suggested the possible influence on neuronal pathways and insulin sensitivity, contributing to obesity and T2D." (PMID 34440368, 2021). "The lower glucose AUC of Iberian pigs (−19% on average) may be related to the greater insulin AUC (+33% on average), a common pattern in many models of obesity." (PMID 33854837, 2021). "Meanwhile, many of these patients with DKD and obesity receiving insulin therapy could benefit from reduced insulin doses with the introduction of these novel cardio and nephroprotective drugs." (PMID 34070103, 2021). "We studied whether high-dose ω-3PUFA supplementation for 3 months improves insulin sensitivity and adipose tissue (AT) inflammation in IR subjects with obesity." (PMID 33753887, 2021). "Brd4-CKO mice displayed improved insulin sensitivity in obesity." (PMID 33830083, 2021). "These alterations are mainly driven by obesity and elevated insulin levels." (PMID 34457110, 2021). "Interestingly, the SRA knockout mouse model displayed an improved insulin sensitivity and resistance to developing obesity in high-fat diet conditions, reduced fatty liver, and improved glucose tolerance." (PMID 34685582, 2021). "The administration of HFD to control mice increased body weight, obesity, serum insulin, and decreased glucose tolerance, whereas HDAC3ΔIEC mice fed by HFD did not develop obesity and showed reduced serum triglyceride levels, less hepatic fat, and smaller adipocytes compared to HFD-fed control mice." (PMID 34203243, 2021). "In addition, obesity complicated by SCH manifests higher insulin levels and low-grade inflammation in patients compared with obesity alone with normal TSH." (PMID 34135958, 2021). "Oxytocin and APP are obesity-specific immune signaling pathways and NK-cell-mediated cytotoxicity, insulin signaling, TCR signaling, ubiquitin-mediated proteolysis, platelet activation BCR signaling, neurotrophin, and oxytocin signaling pathways are T2D immune-system-specific pathways." (PMID 33927693, 2021).
Obesity (continued). "Interestingly, in obesity, the treatment of MGO is associated with defective inhibition of insulin-stimulated AKT in adipose tissue." (PMID 34686659, 2021). "Our study adds novel knowledge from a translational perspective that targeting Drp1‐mediated mitochondrial fission in vivo could be a practical approach in alleviating skeletal muscle insulin resistance and enhancing whole‐body metabolic health in obesity." (PMID 33904649, 2021). "All metabolites found to be discriminative in univariate and multivariate statistical analyses were further investigated using a mixed model with time, insulin response, obesity, glucose response and their interactions as fixed factors (fifth step in univariate analysis)." (PMID 33438144, 2021). "Recent research has identified that at least 7 of these sPLA2s modulate glucose metabolism, presumably by generation of fatty acids or lipoproteins that influence lipid metabolism and mobilization, alterations in fatty acid oxidation, or other mechanisms involved in insulin signaling and obesity." (PMID 34512555, 2021). "This is an important feature as, ω-3 PUFAs can improve impaired metabolism in obesity by modulating main metabolic pathways, such as promoting anti-inflammatory response or insulin sensitivity, regulating the adipocyte apoptosis, or modulating membrane fluidity by altering lipid rafts." (PMID 33922764, 2021). "In addition, CR administration improved the impaired glucose metabolism, insulin action, biochemical obesity parameters, and metabolic profiles in HFD-induced male mice." (PMID 34827919, 2021). "Similarly, lipolysis was found to be sensitive to insulin’s effect in obese and NW adolescents and adults, whereas basal FFAs and their suppression in response to the increment in insulin was reduced in adolescents with obesity compared with lean adults." (PMID 33616083, 2021). "This is suggestive that insulin changes the relationship between obesity and PPD." (PMID 33743677, 2021). "Although palmitoleate has been shown to promote insulin sensitivity, it is however not linked to a decrease in obesity." (PMID 34299261, 2021). "This study provides new insight into the role of CD24 in insulin sensitivity and obesity." (PMID 33467499, 2021). "In that study, the GDM mothers had good glycemic control (55% received metformin and/or insulin treatment resulting in a mean (SD) 5.3% (0.3) HbA1c) and little obesity (median BMI = 24.2, IQR (21.7, 30.3), whereas glycemic status was not known in the other studies." (PMID 34233762, 2021). "A review that summarized current studies on the effects of SCFAs on human health indicated that SCFAs can enter the systemic circulation to affect surrounding tissues, improve blood glucose and insulin sensitivity, and have the function of preventing obesity and related diseases." (PMID 33922631, 2021). "The mechanism behind MetS in promoting EC remains unclear, although it may be attributed to long-term hyperglycemia, obesity, dyslipidemia, insulin, and inflammatory cytokines." (PMID 34975754, 2021). "Furthermore, the inhibition of Drp1-dependent mitochondrial fission in the DVC of HFD-fed rodents prevented hyperphagia and body weight gain and restored insulin sensitivity in a diet-induced obesity model." (PMID 33227495, 2021). "According to some research, adverse effects of obesity on the function of mitochondria and nutrient-signaling pathways might result in an imbalance in insulin and blood glucose." (PMID 34557073, 2021). "As was mentioned in the pathophysiology of obesity, pro-inflammatory mediators, such as leptin, resistin, IL-6, and TNF-α, may cause an adipose tissue dysregulation and a systemic insulin-resistant state." (PMID 34769060, 2021).
Obesity (continued). "Longitudinal studies among adolescents have revealed that higher moderate- to vigorous-intensity physical activity is positively associated with favorable bone health, cardio-metabolic health and fitness, blood lipid profile, blood pressure, insulin sensitivity, and reduced obesity." (PMID 34685449, 2021). "Plasma insulin and glucose levels are also important factors in obesity and hypocholesterolemia." (PMID 34444660, 2021). "Although not all obese patients are insulin resistant, the risk for insulin resistant development seems to directly correlate with increasing overweight/obesity." (PMID 34034759, 2021). "A second study showed HM insulin concentration was negatively associated with infant weight, WLZ, BMI-for-age z-score (BMIAZ), and lean mass in infants from both mothers with normal weight and mothers with obesity at 1 month of age." (PMID 34835980, 2021). "This temporal sequencing is not consistent with the assertion that obesity causes NCDs and premature death by increasing levels of fasting insulin." (PMID 33710289, 2021). "We hypothesize that the exposure to maternal obesity programs offspring islet insulin secretion and pancreatic HSG in a sex-specific manner." (PMID 34108935, 2021). "In addition, these mice had lower fasting levels of insulin and triglyceride but unchanged glucose levels in comparison to wild type mice, providing evidence that adropin overexpression improves insulin sensitivity and glucolipid metabolism in obesity." (PMID 34680524, 2021). "However, several studies reported that acetic acid promoted obesity via hyperphagia and insulin secretion in rodents, and propionic acid impaired insulin action via glucagon secretion." (PMID 33922352, 2021). "Notably, SGMS1-null mice present with insulin secretion deficiencies and mitochondrial dysfunction, whereas SGMS2 knockout mice are protected against high-fat diet-induced obesity and insulin resistance." (PMID 33770195, 2021). "Under these conditions, reactivation of HAND2 expression in obesity could help stimulate adipogenesis and healthy adipose tissue expansion, thus restoring insulin sensitivity and metabolic health." (PMID 34014371, 2021). "Meanwhile, several reports have shown that α-linolenic acid could alleviate obesity and reduce the levels of inflammatory markers, such as serum insulin and leptin, and improve cholesterol homeostasis." (PMID 34950689, 2021). "Further emphasizing the need for future analyses of these genes, reduced expression of Zfhx3 is strongly associated with increased body fat, fat mass, and markers of metabolic syndrome including insulin sensitivity and high cholesterol in mice, suggestive of a role in obesity for this gene." (PMID 34492009, 2021). "The tendency to generate androgen excess, abdominal adiposity, general obesity, insulin disturbances, and other metabolic syndrome symptoms in PCOS women may be altered already prenatally and in the early stages of life." (PMID 34202365, 2021). "These metabolic features mirror clinical studies, which demonstrate that lean human females, who tend to accumulate relatively more subcutaneous adipose fat versus VAT, are more insulin sensitive than lean males, but that aging and obesity erodes IR differences between sexes." (PMID 33692086, 2021). "The associations between insulin levels and 25(OH)D levels were not statistically significant in the general population and stratifications by the class of obesity, but we also found a negative tendency." (PMID 34578857, 2021). "Whether VitD supplements are able to improve either obesity and/or insulin sensitivity should be further investigated in different ethnic population groups." (PMID 34380489, 2021). "Furthermore, our findings suggested that distinct mechanisms dictate insulin resistance under diet-induced obesity in red, white, and mixed muscles." (PMID 34580412, 2021).
Obesity (continued). "In brief, liver-specific mIndy RNAi silencing prevents diet-induced NAFLD in mice; mINDY-KO mice are protected from age- and diet-induced insulin insensitivity and obesity; while antisense oligonucleotides given to rats on a high-fat diet prevent hepatic steatosis and hepatic insulin resistance." (PMID 34677421, 2021). "Previous studies have shown that it contributes to systemic insulin resistance and inflammatory responses, which may occur in obesity." (PMID 34682732, 2021). "Although TAG is the ubiquitous lipid, it has been reported that increased TAG levels are associated with obesity but do not appear to cause insulin resistance." (PMID 34658856, 2021). "We hypothesize that obesity-induced hepatocyte depolarization is communicated through the HVAN to dysregulate insulin secretion and action." (PMID 34192533, 2021). "Gut microbial alterations may cause metabolic consequences, such as additional energy sources and energy regulation, glucose-stimulated insulin secretion, and the release of peptide hormones that control appetite, contributing to obesity." (PMID 34684432, 2021). "Thus, an unfolded protein response ensues, leading to insulin and leptin resistance and subsequently, to obesity and its metabolic consequences." (PMID 33562540, 2021). "In addition, CSF insulin levels are decreased in obese animals and humans and correlate with peripheral insulin sensitivity, creating a link between obesity and central insulin dysregulation." (PMID 34545146, 2021). "Moreover, research of metformin benefit markers will demand to include essential host factors such as circulating insulin and glucose levels, obesity, and expression of OCT1 receptors in the liver and the tumor." (PMID 33531904, 2021). "Depletion of myeloid ANT2 improves insulin sensitivity and glucose tolerance in obesity." (PMID 34676827, 2021). "However, for the overweight/obesity PLWH group the differences in insulin levels were significant in comparison with the other three groups (p<0.0001)." (PMID 34019585, 2021). "Pathologically, obesity caused defective cardiac FAO and induced cardiac lipotoxicity, thereby evoking a set of pathological reactions, including oxidative stress, DNA damage, inflammation and insulin resistance, which contributing to AF." (PMID 34899326, 2021). "Taken together, our findings suggest that TRF restores the obesity-induced alteration in immune cell composition, and this effect may in part contribute to health benefits (including insulin sensitivity) of practicing TRF." (PMID 34836036, 2021). "Insulin infusion in individuals with obesity reduced plasma sICAM-1 and CCL2 levels." (PMID 33692997, 2021). "Deacyl-ghrelin prevents the development of obesity and positively affects insulin sensitivity." (PMID 33959145, 2021). "Indeed, a lipidomic analysis recently performed on primary myocytes from individuals that are insulin-sensitive and lean or insulin-resistant with obesity (OB) also revealed a global phospholipidome down-modulation in OB myotubes." (PMID 34684461, 2021). "All these could lead to disturbance of the glucose-insulin metabolism, substrate oxidation and obesity." (PMID 34779405, 2021). "Hence, it seems evident that obesity-induced inflammation is closely related to the development of T2D, mainly featured by an inefficient action of insulin or insulin resistance, thus placing insulin in the center of the scene." (PMID 33967682, 2021). "As increased ADAM17 expression is correlated with insulin resistance, it is likely that decreasing ADAM17 activity via various therapeutic strategies may increase insulin sensitivity and ultimately have a beneficial effect on obesity." (PMID 33904577, 2021). "The difference in response of males and females to the meal test after four weeks of BYL in diet may be explained by the effects of estradiol, which increases insulin sensitivity and protects against diet-induced obesity and glucose intolerance." (PMID 33503847, 2021).
Obesity (continued). "Whether the state of insulin and/or mTOR signaling is already altered (i.e., by obesity) needs further studies compared to healthy lean subjects with normal insulin sensitivity." (PMID 34956089, 2021). "In addition to chronic hyperglycemia and elevated FFAs, obesity is a major risk factor for T2DM as it desensitizes glucose recipient organs to the action of insulin (obesity-induced IR), leading to increased insulin demand resulting in β-cell dysfunction." (PMID 33918509, 2021). "Due to its proinflammatory, insulin resistant metabolic phenotype that develops concomitant with its extreme, early onset, morbidly obese body type, the Mangalica pig displays great potential to serve as a relevant animal model of obesity." (PMID 34737972, 2021). "Obesity induces an adaptive expansion of β cell mass and insulin secretion abnormality." (PMID 34572101, 2021). "These genes with increase of insulin sensitivity and lipid metabolism, as well as, anorexigenic effects may protect endometriosis patient against obesity." (PMID 34806344, 2021). "In post-obesity, in vivo insulin-induced glucose metabolism is completely normalized." (PMID 34321614, 2021). "From these observations, we propose that the elevation of skeletal muscle ROCK protein by exercise could increase insulin sensitivity in obesity by improving insulin signaling." (PMID 34234788, 2021). "This relationship may be related to decreased transport of insulin across the blood-brain barrier since insulin transport is affected by inflammation, obesity, hyperglycemia, and hypertriglyceridemia." (PMID 34497507, 2021). "Some reasons for the increase of circulating BCAA have been postulated: one is the suppression of the enzymatic catabolism of BCAAs in the adipose tissue and liver of individuals with obesity as, in particular, the insulin-induced impairment of branched-chain α-keto acid dehydrogenase (BCKD)." (PMID 33805234, 2021). "It has been postulated that the underlying mechanisms which could explain the relationship between obesity and reduced handgrip strength are inflammation and insulin resistance." (PMID 33986312, 2021). "Insulin sensitivity, as well as insulin secretion, can be reduced by obesity influence." (PMID 34444990, 2021). "Conversely, despite changes in lipid peroxidation in the liver, the hepatic TGs accumulation and serum AST and ALT levels were not altered following the administration of whole blueberry powder or polyphenolic-rich extracts in diet-induced obesity and insulin resistant mice." (PMID 34439410, 2021). "RBP4 levels are elevated in insulin-resistant mice and humans with obesity and type 2 DM." (PMID 33671547, 2021). "An increase in insulin levels has been observed in obesity and type 2 diabetes." (PMID 34019585, 2021). "Obesity in the transgenic mice IFT88-KOSF−1 was caused by a marked decrease in energy expenditure, hyperphagia (only under HFD feeding), blunted BAT function, insulin resistance, and glucose intolerance." (PMID 34201257, 2021). "This review strongly suggests that supplementation with A. muciniphila is an effective new-generation beneficial bacterium in decreasing obesity parameters, improving insulin sensitivity and glucose homeostasis, modulating energy homeostasis and improving inflammation." (PMID 34065217, 2021). "Therefore, a large number of studies have combined insulin/insulin like growth factor with obesity-related tumors." (PMID 34485124, 2021). "Furthermore, Blnc1 was proposed to decrease pro-inflammatory signaling and obesity-induced inflammation of AT, along with improving insulin sensitivity." (PMID 33800718, 2021). "It plays a key role in lipid metabolism and insulin signaling and thereby obesity." (PMID 34209146, 2021). "In addition, obesity can induce a decreased level of fibroblast growth factor 21 and adiponectin, which results in decreased insulin signaling and β-oxidation in the liver." (PMID 33803020, 2021).